ADCYAP1R1 (ADCYAP receptor type I)
Description:
G protein-coupled receptor activated by the neuropeptide pituitary adenylate cyclase-activating polypeptide (ADCYAP1/PACAP). Binds both PACAP27 and PACAP38 bioactive peptides. Ligand binding causes a conformation change that triggers signaling via guanine nucleotide-binding proteins (G proteins) and modulates the activity of downstream effectors. Activates cAMP-dependent pathway. May regulate the release of adrenocorticotropin, luteinizing hormone, growth hormone, prolactin, epinephrine, and catecholamine. May play a role in spermatogenesis and sperm motility. Causes smooth muscle relaxation and secretion in the gastrointestinal tract.
Synonyms: PAC1R; PAC1; PACAPR; PACAPRI
Tractability: Small molecule: a high-quality ligand is known; it belongs to a druggable protein family. Antibody: its Gene Ontology location is reachable by antibodies, with high confidence; UniProt places it where antibodies can reach, with medium confidence; UniProt predicts a signal peptide or a membrane-spanning region. PROTAC: its protein half-life has been measured; a small molecule that binds it is known.
Gene: Protein-coding gene on chromosome 7 (31,052,308 to 31,111,475, forward strand). Ensembl gene ENSG00000078549.
Subcellular location: Cell membrane
Subcellular location (Human Protein Atlas): Vesicles
Pathways (Reactome):
Signal Transduction: G alpha (s) signalling events; Glucagon-type ligand receptors; NGF-independant TRKA activation
Gene Ontology:
Molecular function: pituitary adenylate cyclase-activating polypeptide receptor activity; protein binding; G protein-coupled peptide receptor activity; peptide hormone binding; signaling receptor activity; adenylate cyclase binding; G protein-coupled receptor activity; small GTPase binding; transmembrane signaling receptor activity; vasoactive intestinal polypeptide receptor activity
Biological process: adenylate cyclase-activating G protein-coupled receptor signaling pathway; adenylate cyclase-modulating G protein-coupled receptor signaling pathway; cell surface receptor signaling pathway; cAMP biosynthetic process; cAMP metabolic process; development of primary female sexual characteristics; G protein-coupled receptor signaling pathway; multicellular organismal response to stress; positive regulation of calcium ion transport into cytosol; positive regulation of inositol phosphate biosynthetic process; positive regulation of small GTPase mediated signal transduction; regulation of cellular response to oxidative stress; response to estradiol; response to ethanol; response to xenobiotic stimulus
Cellular component: plasma membrane; receptor complex; bicellular tight junction; caveola; cell surface; endosome; membrane
Genetic constraint (gnomAD): Loss-of-function variants: 43 observed, 69.6 expected, observed/expected ratio (o/e) 0.62, 90% interval 0.48 to 0.8. The upper end of that interval is the gene's LOEUF score, 0.8, which puts it in group 3 of 6, group 1 being the genes least tolerant of losing a copy. Missense variants: 472 observed, 603.88 expected, observed/expected ratio (o/e) 0.78, 90% interval 0.72 to 0.84. Synonymous variants: 221 observed, 228.39 expected, observed/expected ratio (o/e) 0.97, 90% interval 0.87 to 1.08.
Homologues: Orthologues: chimpanzee ADCYAP1R1 (100% identical), chimpanzee ADCYAP1R1 (99% identical), macaque ADCYAP1R1 (97% identical), dog ADCYAP1R1 (94% identical), mouse Adcyap1r1 (93% identical), rat Adcyap1r1 (93% identical), guinea pig ADCYAP1R1 (91% identical), rabbit ADCYAP1R1 (85% identical), tropical clawed frog adcyap1r1 (77% identical), pig ADCYAP1R1 (73% identical), zebrafish adcyap1r1b (72% identical), zebrafish adcyap1r1a (55% identical). Paralogues in human: VIPR1 (47% identical), VIPR2 (47% identical), SCTR (44% identical), GHRHR (38% identical), PTH1R (36% identical), GLP1R (33% identical), GCGR (32% identical), GIPR (32% identical), GLP2R (32% identical), PTH2R (32% identical), CALCR (26% identical), CALCRL (25% identical), and 30 more.
Diseases named in the same sentence as ADCYAP1R1 in open-access papers:
ADCYAP1R1 is named in the same sentence as 87 diseases in open-access papers, as found by Europe PMC text mining. Sharing a sentence is not in itself a finding about the gene and the disease. The quoted sentences say what the papers report.
Anxiety (17 papers, 2012 to 2026). Intense feelings of nervousness, tension, or panic often arise in response to interpersonal stresses. "We also hypothesized that altered Adcyap1 and Adcyap1r1/PAC1R content of the EWcp may be associated with increased anxiety and a depression-like state." (PMID 37511603, 2023). "The results indicated that Atp6v1f, Arpc5, Adcyap1r1, Ndufb6, and Psmc6 were distinctly dysregulated in the hypothalamus of the depression-susceptible group, while Gys1, Pgp, Klc1, Chka, Ncstn, Ndufa6, and Kyat1 were distinctly dysregulated in the anxiety-susceptible group." (PMID 33737865, 2021). "Interestingly, some of the linear dose-response DEGs have been implicated in transmission and plasticity (GRIN2A, GAD2), depression and antidepressant effect (DDIT4, GAD2) anxiety and stress responses (ADCYAP1R1), WNT signalling (FRZB), neurogenesis (ARHGEF39) and hippocampal volume (ANKRD37)." (PMID 39055655, 2024).
post-traumatic stress disorder (17 papers, 2011 to 2025). An anxiety disorder precipitated by an experience of intense fear or horror while exposed to a traumatic (especially life-threatening) event. "CpG methylation patterns within ADCYAP1R1 (receptor for adenylate cyclase), leading to polypeptide overexpression, are implicated in people suffering from posttraumatic stress disorder (PTSD) and anxiety." (PMID 32973872, 2020). "The pituitary adenylate cyclase-activating polypeptide receptor (PAC1, also known as ADCYAP1R1) is associated with post-traumatic stress disorder and modulation of stress response in general." (PMID 32533011, 2020). "ADCYAP1R1 encodes a pituitary adenylate cyclase-activating polypeptide receptor that in humans is strongly expressed in the amygdala and hippocampus, and is associated with fear response, threat stimuli, post-traumatic stress disorder and other anxiety disorders." (PMID 26691338, 2015). "Methylation of the ADCYAP1R1 gene in peripheral blood DNA was found to be associated with post-traumatic stress disorder (PTSD) and methylation of FKBP5 in lymphocytes was associated with both genetic risk for PTSD and early life adversity." (PMID 24691403, 2014).
depression (7 papers, 2020 to 2025). "The expressions of Atp6v1f, Arpc5, Ndufb6, and Psmc6 were significantly down-regulated while Adcyap1r1 was up-regulated in the depression-susceptible group compared with the control group." (PMID 33737865, 2021). "In this module, ADCYAP1R1, PRKACA, MAPK8, MAPK14, GRIA1, and FOS are both targeted genes of CGFC and pathogenic genes of depression; RHOA is a specific targeted gene of CGFC, and most of these genes are related to the pathogenesis or treatment of depression." (PMID 34867413, 2021).
Cluster headache (4 papers, 2017 to 2025). A type of headache characterized by repeated attacks of unilateral pain lasting 15 to 180 minutes and associated with local autonomic signs. "Moreover, we found evidence of suggestive association among previously suggested loci to be involved in cluster headache, including LINC01877, LINC01705, ADCYAP1R1, and MME." (PMID 36404298, 2022).
melanoma (3 papers, 2021 to 2025). A malignant, usually aggressive tumor composed of atypical, neoplastic melanocytes. "Six genes closely associated with the prognosis of melanoma patients, including ADCYAP1R1, GPI, IFITM1, KIR2DL4, LIF and NTS, were elected to fabricate a prognosis model." (PMID 38217549, 2024). "In this study, six genes (ADCYAP1R1, GPI, IFITM1, KIR2DL4, LIF, and NTS) were identified as being closely associated with prognosis among a pool of 1793 melanoma-related genes." (PMID 38217549, 2024). "Our findings indicate that ADCYAP1R1, GPI, and NTS may contribute to a poor prognosis in melanoma patients, while IFITM1, KIR2DL4, and LIF are more likely to be associated with a better prognosis in individuals with melanoma." (PMID 38217549, 2024). "In this study, six genes (ADCYAP1R1, GPI, IFITM1, KIR2DL4, LIF, and NTS) that exhibited strong correlation with the prognosis of melanoma patients were identified." (PMID 38217549, 2024). "Obviously, ADCYAP1R1, GPI and NTS might lead to poor prognosis for melanoma patients, while IFITM1, KIR2DL4 and LIF are more likely to improve outcomes." (PMID 38217549, 2024).
stress-related disorder (3 papers, 2017 to 2026). Stress-related disorders are mental health disorders that are a result of an atypical response to both short and long-term anxiety due to physical, mental, or emotional stress. "The receptor (ADCYAP1R1, hereafter referred to as PAC1R) of the pituitary adenylate cyclase-activating peptide (PACAP), an emerging therapeutic target for stress-related disorders, is a good example." (PMID 35847975, 2022).
asthma (2 papers, 2015 to 2023). "Chen and colleagues found that increased methylation of a single CpG in the ADCYAP1R1 promoter is associated with an increased risk of asthma for Puerto Rican children, particularly for children exposed to violence." (PMID 25741380, 2015). "A study among Puerto Rican children exposed to violence showed an association between greater methylation of the anxiety regulating gene, ADCYAP1R1, and asthma." (PMID 36973960, 2023).
type 1 diabetes mellitus (2 papers, 2017 to 2023). A chronic condition characterized by minimal or absent production of insulin by the pancreas. "Moreover, relevant pathways related to type I diabetes mellitus (PTPRN2), insulin resistance (RPS6KA2), and insulin secretion (ADCYAP1R1) were also identified." (PMID 37415231, 2023). "Finally, our enrichment analysis identified within our DMPs, relevant pathways related to type I diabetes mellitus (PTPRN2) insulin resistance (RPS6KA2) and secretion (ADCYAP1R1)." (PMID 37415231, 2023).
breast carcinoma (1 paper, 2023). "For the five FTD-Breast cancer comorbid genes (AKT3, GFAP, C4A, VDAC1, ADCYAP1R1), we analyzed the alterations in the genetic profiles among the different subtypes of Breast cancer." (PMID 37834358, 2023). "Our results showed that the genes AKT3, GFAP, ADCYAP1R1, VDAC1, and C4A have significant transcriptomic alterations in FTD along with the comorbidity status with COVID-19 and breast cancer." (PMID 37834358, 2023). "Overall, we found two novel FTD-COVID-19 comorbid genes, GFAP and RTN4, and five novel FTD-Breast cancer comorbid genes, AKT3, GFAP, ADCYAP1R1, VDAC1, and C4A, in this study." (PMID 37834358, 2023).
breast invasive carcinoma (1 paper, 2023). "Results from the survival analysis showed that the up-regulated genes AKT3 and VDAC1 and the down-regulated genes ADCYAP1R1, GFAP, and C4A were found to be significantly associated with the overall survival of the patients with breast invasive carcinoma." (PMID 37834358, 2023). "We found that the FTD DEGs, AKT3, UBE2N, VDAC1, ADCYAP1R1, C4A, and GFAP showed significant comorbidity in breast invasive carcinoma patients at a p-value < 0.05." (PMID 37834358, 2023).
cervical cancer (1 paper, 2024). A primary or metastatic malignant neoplasm involving the cervix. "In the case of ADCYAP1R1, its ligand (ADCYAP1) has been previously reported as transcriptionally silenced in cervical cancer." (PMID 38540371, 2024).
esophageal cancer (1 paper, 2021). A primary or metastatic malignant neoplasm involving the esophagus. "Survival univariate/multivariate COX analysis revealed that five genes, ZBTB16, AQP4, ADCYAP1R1, PDGFD, and VIPR2, and two microRNAs, miR-99a-5p, and miR-508-5p, were related to esophageal cancer prognosis." (PMID 34329340, 2021).
kidney failure (1 paper, 2025). An acute or chronic condition that is characterized by the inability of the kidneys to adequately filter the blood. "Sixty-nine significant associations between genetic loci and the clustered traits originated from candidate gene studies with replication, including associations such as ADCYAP1R1 with survival,22BCL2 with kidney failure, and CXCL1 with infection/sepsis." (PMID 40168842, 2025).
mental disorder (1 paper, 2023). A disease that has its basis in the disruption of mental process. "Other candidate genes, including ADCYAP1R1, NAP1L4, and ERBB4, have been reported in mental disorders." (PMID 37491364, 2023).
uterine cancer (1 paper, 2024). Primary or metastatic malignant neoplasm involving the uterine corpus and/or the cervix. "The DIANA-Tarbase documents these miRNAs as regulators of VWCE and ADCYAP1R1, respectively, potentially reinforcing the involvement of these genes in uterine cancer." (PMID 38540371, 2024).
tumor (7 papers, 2005 to 2024). "Finally, PGLYRP3, GAL, ADCYAP1R1 and LIF were selected to construct the Tumor Mutation Burden Immune Prognostic model (TMB-IP) using the following formula: TMB-IP score = (PGLYRP3*0.0988045135949462 + GAL*0.0483710471635067 + ADCYAP1R1*0.123387518699318 − LIF*0.121787959868336)." (PMID 33836680, 2021).
cancer (5 papers, 2018 to 2024). A tumor composed of atypical neoplastic, often pleomorphic cells that invade other tissues. "The candidate gene obtained by these two methods has only one intersection gene (ADCYAP1R1), which is a common differential methylation gene among three cancers, COAD, PAAD and ESCA." (PMID 31888612, 2019).
neurological disease (2 papers, 2012 to 2022). "Ntrk3, adenylate cyclase activating polypeptide 1 receptor 1 (Adcyap1r1), E2F transcription factor 1 (E2f1) and X-ray repair in Chinese hamster cells 6 (Xrcc6) were represented within the “neurological disease” pathway." (PMID 22934110, 2012).
ADCYAP1R1 also shares sentences with these, for which no sentence is quoted: migraine (42 papers); Headache (6); Parkinson disease (5); psychiatric disorder (5); schizophrenia (5); Alzheimer disease (4); anxiety disorder (4); neurodegenerative disease (4); Stroke (4); amyotrophic lateral sclerosis (2); atherosclerosis (2); colon cancer (2); cystitis (2); Huntington disease (2); infection (2); insulinoma (2); metabolic syndrome (2); neuroblastoma (2); Parkinson’s (2); primary pulmonary hypertension (2); pulmonary hypertension (2); tauopathies (2); acute endometritis (1); ADNP syndrome (1); alcohol abuse (1); alcoholism (1); autism spectrum disorder (1); cardiac disease (1); cardiovascular diseases (1); Cerebral ischemia (1).
A further 39 diseases each share a sentence with ADCYAP1R1 in 1 paper.